PLEC (plectin)
Diseases named in the same sentence as PLEC in open-access papers (continued):
Sharing a sentence is not in itself a finding about the gene and the disease.
ovarian carcinoma (continued). "Moreover, immunoblot detection of plectin in the cell surface fraction of ovarian cancer cell lines (SKOV3 and OVCAR8) showed high expression compared to healthy human fallopian tube epithelial cells (FT132)." (PMID 34571895, 2021). "Further characterization revealed ovarian cancer, bile duct cholangiocarcinoma, lung adenocarcinoma, lung squamous cell carcinoma, and head and neck cell carcinoma to be positive for cancer-specific plectin (CSP) expression." (PMID 34571866, 2021). "Plectin shows strong membrane staining in pancreatic cancer and is significant in other cancers including bile duct cholangiocarcinoma, lung adenocarcinoma, lung squamous cell carcinoma, ovarian cancer, and intestinal type stomach cancer." (PMID 21811618, 2011). "Moreover, proteomic analysis with ovarian cancer SKOV3 cells revealed reduced plectin expression after treatment with immunotherapies, protein aggregate magnesium-ammonium phospholinoleate-palmitoleate anhydride (P-MAPA), and interleukin-12 as single agents or in combination." (PMID 34571895, 2021). "Plectin expression is modulated by ECM stiffness and correlates significantly with clinical prognosis in ovarian cancer patients." (PMID 41011568, 2025). "We validated the expression of proteins of interest (COL12A1, FUBP1, PLEC, SLC4A1, and TKT) using immunohistochemistry (IHC) and further characterized their expression in online ovarian cancer databases." (PMID 40565351, 2025). "We have recently shown the expression of PLEC, PPL, and EVPL in benign and malignant ovarian tumours." (PMID 39682273, 2024). "Plectin is highly expressed and localized on the cell surface of advanced ovarian cancer, and the plectin-targeting peptide (PTP) has been demonstrated to specifically target cell surface plectin." (PMID 36015275, 2022). "In this study we demonstrate that the elevation of Oct4A at the mRNA level correlates with the enhancement in TUBB2A, PLEC and VIM expression in parental HEY, SKOV3 and OVCAR5 ovarian cancer cell lines in response to paclitaxel or cisplatin treatments." (PMID 28406185, 2017). "Moreover, several Tip60-targeted Khib were identified on cancer biomarkers, such as plectin (PLEC, related to ovarian cancer), alcohol dehydrogenase class-3 (ADH5, related to breast cancer), and PARK7 (related to lung cancer), which therefore links Tip60 and the Khib pathway to cancer." (PMID 35178156, 2022).
pancreatic cancer (16 papers, 2011 to 2025). "Bovine serum albumin superparamagnetic iron oxide nanoparticles (BSA·SPIONs) conjugated with near infra-red fluorescent dyes, Cy5 or Cy7, and monoclonal anti-plectin antibody specifically were shown to associate with CSF-plectin in pancreatic cancer cells and mice tissue." (PMID 36612146, 2022). "published a groundbreaking article titled “Unexpected gain of function for the scaffolding protein plectin due to mislocalization in pancreatic cancer”, which is considered one of the most significant and influential contributions in this field." (PMID 38720811, 2024). "Although many reports have proven the specificity of the PTP peptide for plectin, most studies have focused on pancreatic cancer." (PMID 35631582, 2022). "Its imaging performance in pancreatic cancer and several types of tumors with different plectin expression levels was investigated." (PMID 35631582, 2022). "Plectin-1 is identified as a receptor explicitly overexpressed on pancreatic cancer cell surface and has been extensively explored as a potential biomarker since its advent." (PMID 35135558, 2022). "Plectin-1 protein, a novel biomarker for pancreatic cancer detection provides and maintains cellular mechanical integrity." (PMID 35135558, 2022). "While the expected localization of plectin is cytoplasmic, cell surface expression in pancreatic cancer had been reported (via exosomes secreted from cancer cells), playing a role in growth of pancreatic cancer xenografts in immunodeficient mice." (PMID 31628412, 2019). "The PTP peptide was identified by phage display on primary pancreatic cancer cell lines and its binding partner (plectin-1) was found on all primary and metastasized PDAC specimens tested to date." (PMID 23616947, 2013). "Another interesting novel pancreatic cancer specific protein, plectin, was identified through our method." (PMID 21811618, 2011). "Experiments are underway to determine the mechanism of the cell surface population of plectin and its potential role in pancreatic cancer." (PMID 21811618, 2011). "In addition, our recent work exhibits the overexpression of plectin-1 in both primary and immortalized pancreatic cancer cell lines including Panc1 and AsPC-1." (PMID 35135558, 2022). "Moreover, a monoclonal antibody (mAb) was linked to the BSA equipped SPIONs of high specificity in recognition of Plectin-1, a specific biomarker for pancreatic cancer cells." (PMID 33803884, 2021). "PLEC (Plectin) was further found to be up-regulated in squamous cell carcinoma, aiding in the induction of malignant transformation from sinonasal inverted papilloma and has been utilised in pancreatic cancer detection using targeted nanoparticles." (PMID 33048956, 2020). "Thus AAV vectors can successfully be modified to deliver genes specifically to pancreatic cancer cells using the cancer cell-specific property of cell surface localization of plectin-1." (PMID 23616947, 2013). "In addition, in pancreatic cancer unexpected extracellular surface expression of Plectin has recently been reported and this was shown to be necessary for exosome production in conjunction with proteins Rab27a and −b and required for sustaining tumor growth in immunocompetent mouse models." (PMID 27470985, 2016). "Recently, plectin was shown to be expressed in all pancreatic cancers examined, but has no expression in the healthy pancreas or in other benign conditions." (PMID 21811618, 2011). "Herein, we used pancreatic cancer (PDAC) cell lines including Panc1, AsPC-1 and endothelial cell (HUVECs) to understand the receptor-dependent and -independent endocytosis of two different GNPs derived using plectin-1 targeting peptide (PTP-GNP) and corresponding scrambled peptide (sPEP-GNP)." (PMID 35135558, 2022).
breast carcinoma (15 papers, 2020 to 2025). "Additionally, previous studies have shown that ablation of plectin (PLEC) is associated with impaired cell migration in breast cancer cells, highlighting its potential role in tumor progression." (PMID 40312292, 2025). "Although high expression of vimentin is associated with poor recurrence-free survival of breast cancer patients, it is unclear whether simultaneous high expression of both vimentin and plectin leads to a worse scenario." (PMID 39542246, 2024). "In breast cancer, siRNA-mediated depletion of plectin suppresses migration, invasion, and adhesion, attenuating tumor growth and metastasis via the NF-κB1/CXCL9 axis." (PMID 41011568, 2025). "Moreover, SNRPA1-mediated alternative splicing of exon 31 produces gliadin-like plectin isoforms with pro-metastatic properties, promoting lung colonization in breast cancer by modulating focal adhesions." (PMID 41011568, 2025). "Notably, plectin is significantly upregulated in inflammatory breast cancer cells exhibiting EGFR+ expression, where it modulates cell migration through the integrin/EGFR signaling axis." (PMID 41011568, 2025). "In breast cancer, the oncogenic protein FAM83A interacts with plectin, modulating cytoskeletal architecture and activating downstream signaling pathways that promote cell survival and proliferation." (PMID 41011568, 2025). "On the other hand, low expression of plectin promotes progression in several tumors, including BCC, SCC, and breast cancer." (PMID 39334817, 2024). "To confirm this finding, we inspected the intracellular localization of plectin in epithelial monolayers grown from MDCK cells, mouse cholangiocytes, and epithelial breast cancer cells (MCF-7) using immunofluorescence microscopy." (PMID 35139142, 2022). "Mutant plectin (PLEC), marker Of Proliferation Ki-67 (MKI67), HEAT Repeat Containing 1 (HEATR1) and AHNAK nucleoprotein (AHNAK) were detected in three of the four breast cancer cell lines." (PMID 33274046, 2020). "Indeed, DDR1i caused differential expression in several direct RUNX1 target genes including DUT, an essential nucleotide metabolism enzyme seen upregulated across breast cancers, and MYC, along with ANP32B, PLEC, CEBPD, ID1, and STAT3." (PMID 40614729, 2025). "To elucidate whether EpOME promotes breast cancer progression by mediating PLEC, we established stable MDA-MB-231 and MCF-7 cells with knockdown of PLEC." (PMID 39695149, 2024). "Interestingly, in CD95- or tumor necrosis factor (TNF)-induced apoptosis of human breast cancer cell line MCF7, plectin was shown to be an early binding partner of active caspase 8, which results in cleavage of plectin." (PMID 34571895, 2021). "Similarly, ablation of plectin impaired cell migration in HNSCC, NSCLC, and breast cancer cell lines." (PMID 34571895, 2021).
epidermolysis bullosa (10 papers, 2010 to 2024). Epidermolysis bullosa (EB) is a group of genetic skin diseases that cause the skin to blister very easily. "The PLEC mutation causes epidermolysis bullosa, in which osteoporosis is one of the main comorbidities." (PMID 37461309, 2023). "Patients that have mutations in plectin have a severe skin blistering disease, epidermolysis bullosa, underscoring the importance of plectin to the hemidesmosome and cell-cell junctions." (PMID 21811618, 2011). "Significantly enriched keywords associated with our group of genes were Epidermolysis bullosa due to four genes with variants in our study group (EXPH5, PLEC, COL7A1, LAMB3)." (PMID 36454308, 2023). "Epidermolysis bullosa (EB) is a group of diseases resulting in blistering in the BM and skin fragility in which Ln-332, plectin, integrin α6, BP180 or collagen type VII may be affected." (PMID 20230631, 2010).
hepatocellular carcinoma (10 papers, 2015 to 2025). A malignant tumor that arises from hepatocytes. "Plectin elevation in tumor hepatocytes is associated with hepatocellular carcinoma (HCC) progression and poor prognosis." (PMID 40052672, 2025). "It has also been previously reported that KRT18 interacts with several structural proteins in hepatocellular carcinoma including plectin, which is a multifunctional cytoplasmic cross-linked protein with multiple binding sites for cytoskeletal components." (PMID 40475465, 2025). "Intermediate filament extracts from liver and hepatoma tissues exhibited irregular bundling of keratin fibers, suggesting that plectin deficiency impacts filament bundle integrity." (PMID 39334817, 2024). "The loss of K8/K18 as a cytoskeletal protein in hepatocellular carcinoma led to the malposition of plectin and RACK1, as well as affected the activation of the PKC signaling pathway." (PMID 39502314, 2024). "Plectin deficiency in hepatocellular carcinoma results in abnormal expression of cytokeratin 18 and disassembled hemidesmosome." (PMID 25774093, 2015). "Therefore, a convincing explanation is that downregulated plectin affects K18 expression in hepatocellular carcinoma tumorigenesis, causing cytoskeletal disturbance, nuclear instability, and vulnerability." (PMID 39502314, 2024). "Plectin-deficient human hepatic cells exhibit higher cell motility associated with increase in focal adhesion kinase activity that are comparable to the properties of invasive hepatocellular carcinoma." (PMID 25774093, 2015). "Our previous studies demonstrated that plectin-deficiency-mediated pleomorphism is associated with an altered level of CK18 expression in human hepatocellular carcinoma (HCC)." (PMID 25774093, 2015). "Consistent with this idea, plectin mRNA has been found to be upregulated in liver carcinomas, especially in the later stages of disease." (PMID 40052672, 2025). "Disruption of cytoskeletal networks upon plectin inactivation accounts for reduced contractility and aberrant adhesions in hepatocellular carcinoma (HCC) cells." (PMID 40052672, 2025). "Plectin links the migration potential of hepatocellular carcinoma (HCC) cells to cell shape dynamics." (PMID 40052672, 2025). "Further to that, in hepatocellular carcinoma (HCC) cell lines, PLEC deficiency results in irregular loosened bundles of intermediate filaments leading to observable pleomorphism." (PMID 34001250, 2021). "Plectin inactivation inhibits hepatocellular carcinoma (HCC) invasion and metastasis." (PMID 40052672, 2025). "Moreover, compared with normal liver tissues and cells, plectin expression is significantly increased in hepatocellular carcinoma (HCC) tissues and cells." (PMID 39334817, 2024). "Similarly, hepatoma cell lines with lower plectin expression, PLC/PRF/5, and HepG2 demonstrated higher migration rates than cells with higher plectin expression, the Chang liver cells." (PMID 34571895, 2021). "All the previous results discussed in this report support our hypothesis that plectin may be correlated with the regulation of cell motility involved in the invasiveness of hepatic carcinoma." (PMID 25774093, 2015). "It implied that decreased plectin expression is accompanied with human hepatic carcinoma." (PMID 25774093, 2015). "CRISPR/Cas9- or Plecstatin-1 (PST)-mediated plectin inactivation attenuates hepatocellular carcinoma (HCC) oncogenic potential through FAK, Erk1/2, and PI3K/Akt axis." (PMID 40052672, 2025). "In this study, we aim to investigate the role of plectin in the migration of hepatocellular carcinoma (HCC) cells and explore its relevant molecular mechanism." (PMID 36613521, 2022). "Here, we dissected PST's mode of action using knockouts of plectin (PLEC) and ODF2 in SNU-475 hepatocellular carcinoma (HCC) cells." (PMID 41467448, 2025).
hepatocellular carcinoma (continued). "In contrast to the numerous reports of plectin’s overexpression in cancer, differing observations have been made in hepatocellular carcinoma (HCC) and carcinoma of the skin, highlighting the importance of elucidating tissue-specific or context-dependent exceptions." (PMID 34571895, 2021). "(A) Meta-analysis of differential plectin (PLEC) mRNA expression in non-tumor (NT) liver and hepatocellular carcinoma (HCC) patients." (PMID 40052672, 2025).
pancreatic ductal adenocarcinoma (10 papers, 2019 to 2025). An infiltrating adenocarcinoma that arises from the epithelial cells of the pancreas. "Additional examples are the CV-1 peptide targeting CD44 in gastric tumors, plectin-1 targeted peptides for pancreatic ductal adenocarcinoma (PDAC), and hepsin-specific peptides for prostate cancer imaging and detection." (PMID 41008874, 2025). "While the release of plectin from pancreatic ductal adenocarcinoma cell lines has been confirmed to occur via exosomes, the mechanism of plectin release from astrocytes and GBMs remains to be elucidated." (PMID 38263015, 2024). "Furthermore, in agreement with the reported release of plectin from various pancreatic ductal adenocarcinoma cell lines, we observed an increased release of plectin from U-251 MG cells." (PMID 38263015, 2024). "Plectin is a biomarker for invasive pancreatic ductal adenocarcinoma." (PMID 31430912, 2019). "In addition, previous research proved that the PLEC gene could serve as a novel biomarker to identify preinvasive, primary, and metastatic pancreatic ductal adenocarcinoma, and its expression was continuously increasing along with tumor progression." (PMID 35712127, 2022). "A plectin-1 targeted peptide (PTP) that binds to plectin-1, a marker of pancreatic ductal adenocarcinoma (PDAC), has been applied as a targeted imaging agent." (PMID 41008874, 2025). "In pancreatic ductal adenocarcinoma (PDAC), Plectin-1, a cytoskeletal protein, has emerged as a novel biomarker." (PMID 39843495, 2025). "Moreover, the expression of plectin, like that of vimentin, is upregulated in different types of carcinoma cells and tumor tissues, and curiously, plectin, has been localized on the extracellular surface of pancreatic ductal adenocarcinoma and other cancer cells." (PMID 34440923, 2021).